AR (androgen receptor)
Diseases named in the same sentence as AR in open-access papers (continued):
Sharing a sentence is not in itself a finding about the gene and the disease.
melanoma (continued). "Translational efforts to AR-targeted therapies in melanoma treatment are gaining momentum." (PMID 40940929, 2025). "Thus, further studies are needed to refine our understanding of how AR interacts with melanoma subtypes, tumor microenvironment components, and immune modulators, which will be critical for maximizing the clinical benefit of AR targeting." (PMID 40940929, 2025). "Therefore, we firstly analyzed the role of the androgen/AR axis in motility and invasiveness of melanoma cells." (PMID 39837817, 2025). "The finding that blockade of AR by somatic knockdown or antagonists reverse the androgen-elicited effects on melanoma cell locomotion and 3D models, further reinforce the role of receptor in the androgen signaling leading to melanoma aggressiveness." (PMID 39837817, 2025). "AR also increased melanoma invasion through regulating the miRNA-539-3p/USP13/MITF/AXL signals." (PMID 41228208, 2025). "More recent molecular studies have shown AR expression in melanoma cell lines and tumors." (PMID 41228208, 2025). "Understanding AR’s role in melanoma could lead to new treatment options, particularly for sex-specific patient groups." (PMID 40940929, 2025). "However, little is known about AR expression and its effects on immune cell recruitment in melanoma." (PMID 40940929, 2025). "The side effects of AR-targeted therapies warrant particular attention in melanoma." (PMID 40940929, 2025). "Therefore, we investigated the impact of AR in melanoma responsiveness to immunocheckpoint blockade." (PMID 39837817, 2025). "AR exhibits a seemingly controversial role in melanoma development and survival." (PMID 41228208, 2025). "Furthermore, utilizing an in vivo melanoma metastasis model, they demonstrated that AR increases melanoma lung metastasis by modifying MITF." (PMID 40940929, 2025). "Furthermore, AR antagonists improve the response to BRAF/MEK-targeted therapy in preclinical models of melanoma." (PMID 39837817, 2025). "Furthermore, several genes involved in melanogenesis, differentiation, and melanoma progression were upregulated or downregulated following AR silencing." (PMID 40940929, 2025). "Together, these observations functionally verify our phosphoproteomic analyses highlighting the enrichment of cell division-related pathways as AR-dependent, FUT4-independent as opposed to the enrichment of cell adhesion-/motility-related pathways as AR-/FUT4-dependent signaling in melanoma cells." (PMID 38326303, 2024). "To delineate the key FUT4-fucosylated target(s) mediating pro-invasive signaling in AR+ melanoma cells, we performed comparative proteomic profiling of fucosylated proteins purified from WM793 cells that ectopically expressed FUT4 vs. those that were knocked down for FUT4." (PMID 38326303, 2024). "However, considering the severe side effects of AR inhibition, it will be crucial to develop effective stratification methods for melanoma patients." (PMID 38326303, 2024). "Together, these data indicate that AR-driven FUT4 signaling alters cell:cell adhesion by disrupting N-cadherin:catenin-containing junctional complexes between melanoma cells, supporting the notion that androgen/AR-FUT4 signaling promotes melanoma motility by altering cellular adhesion complexes." (PMID 38326303, 2024). "By delineating key androgen-triggered signaling that enhances metastatic aggressiveness, our findings help explain sex-associated clinical outcome disparities and highlight AR/FUT4 and its effectors as potential prognostic biomarkers and therapeutic targets in melanoma." (PMID 38326303, 2024).
melanoma (continued). "Disruption of the androgen–AR axis, either through surgical castration or with abiraterone, significantly enhanced T cell anti-tumor activity in male mice and improved the efficacy of anti-PD-1 immunotherapy in bladder cancer, colorectal cancer, and melanoma." (PMID 39682229, 2024). "For instance, the androgens/AR signaling has been found to suppress T cell immunity against cancer in males, resulting in faster tumor progression compared to females in colorectal cancer and melanoma." (PMID 39582864, 2024). "Therefore, our study delineates for the first time the pathological transcriptional regulation of FUT4 by AR and their downstream effectors and functional contributions to the metastatic spread of human cancer (melanoma)." (PMID 38326303, 2024). "Our findings point to targeting AR as possible co-therapeutical approach in melanoma treatment." (PMID 37838724, 2023). "Overexpressing AR in melanoma A375 and WM115 cells significantly decreases MITF protein levels." (PMID 37070131, 2023). "In order to examine whether AR plays a role in such sex difference, melanoma patients are grouped by their tumor AR protein levels." (PMID 36833272, 2023). "Importantly, the AR gene was among the top five target genes bound by AR in DAB-treated A375 melanoma cells." (PMID 37838724, 2023). "A similar plot might control the aggressiveness of BC and melanoma that express AR at different degree." (PMID 36941697, 2023). "We found that pronounced induction of AR expression occurred in a panel of primary and established melanoma cells already by 48 hours of treatment with DAB and other BRAF and MEK inhibitors, while inhibitors of other key signaling pathways, such as NF-κB, STAT3, and AP-1 exerted no such effect." (PMID 37838724, 2023). "We previously showed that basal AR activity is required for sustained proliferation and tumorigenesis of melanoma cells, with AR functioning as a bridge between RNA-Pol II and DNA repair proteins and ensuring the continuous DNA repair process associated with gene transcription." (PMID 37838724, 2023). "Thus, increased AR expression in melanoma cells elicits changes found in a BRAFi-tolerant subpopulation and enhanced EGFR and SERPINE1 expression of likely clinical significance." (PMID 37838724, 2023). "Similarly, in a study on the heterogeneity of melanoma cell lines and tumors, AR expression was found to cluster together with EGFR and SERPINE1 in an undifferentiated AXL positive subgroup connected with targeted drug resistance." (PMID 37838724, 2023). "The markedly increased AR expression that is already occurring at early times of BRAFi and MEKi exposure suggested that this molecule can fulfill a second distinct function in melanoma cells as part of an adaptive mechanism leading to targeted drug resistance." (PMID 37838724, 2023). "Indeed, it can induce melanoma cell growth via androgen receptor (AR) since genetic and pharmacological suppression of AR activity in melanoma cells blunts their proliferation, while increased AR expression or activation exerts opposite effects." (PMID 36286041, 2022). "A study based on analysis of clinical samples and melanoma cells from male and female patients showed that genetic and pharmacological suppression of AR activity triggers melanoma cell senescence and limits tumorigenesis, while increased AR expression or activation exert opposite effects." (PMID 36614041, 2022). "As previously reported, the major committed for the worse melanoma prognosis of males versus females could be the higher level of testosterone, which in turn activates AR." (PMID 36286041, 2022). "Androgen receptor (AR) involves in the development of melanoma." (PMID 33875645, 2021). "A significantly higher proportion of infiltrating B cells, CD4+ and CD8+ T cells, and macrophages was found in melanomas with a positive association with the AR gene-silencing signature than in those with a negative association." (PMID 33112375, 2021).
melanoma (continued). "Thus, besides being required, increased AR signaling is a positive determinant of melanoma cell proliferation." (PMID 33112375, 2021). "Opposite modulation of these genes could contribute to the growth-promoting effects exerted by increased AR activity in melanoma cells as well as primary melanocytes." (PMID 33112375, 2021). "This is consistent with bioinformatic analysis of large melanoma datasets sorted by the AR gene-silencing signature that we have established, as well as experimental findings with tumors formed by melanoma cells with or without AR loss." (PMID 33112375, 2021). "Androgen receptor (AR) promotes melanoma metastasis by altering miRNA-539-3p/USP13/MITF/AXL signal." (PMID 35003328, 2021). "However, our findings clearly indicate that melanoma cells of both male and female individuals are equally dependent on sustained AR signaling for proliferation, maintenance of genomic stability, and tumorigenesis." (PMID 33112375, 2021). "The resulting enhancement of endogenous DNA damage suggests that already approved AR inhibitors could be used in new combination approaches for melanoma treatment." (PMID 33112375, 2021). "A significant concordance was found between the AR silencing gene signature and the iLINCS-derived transcriptional profiles of A375 melanoma cells treated with several AR inhibitors, as well as a number of DNA-damaging agents targeting the topoisomerase 2 (TOPO2) and TOPO1 enzymes." (PMID 33112375, 2021). "AR signaling in this setting was implicated in the control of melanoma cells’ invasive properties, without any effect on proliferation." (PMID 33112375, 2021). "Conversely to the growth suppressing effects of the AR inhibitors, proliferation of primary melanocytes and melanoma cells in charcoal-stripped medium was significantly enhanced by treatment with the AR agonist dihydrotestosterone (DHT) in a dose-dependent manner." (PMID 33112375, 2021). "Surprisingly little is known about the role of AR signaling in melanoma." (PMID 33112375, 2021). "In melanoma development, the consequences on cancer cells are likely prevalent, since in coculture assays of melanoma cells and dermal fibroblasts, a potent AR inhibitor exerted net beneficial effects that paralleled those observed in vivo, in an orthotopic model of melanoma formation." (PMID 33112375, 2021). "Taking into consideration the involvement of SLNCR1 in the regulation of transcription program of melanoma, blocking the AR-SLNCR1 interaction with specific oligonucleotides might be an attractive therapeutic strategy in the future." (PMID 34638331, 2021). "SLNCR1/AR promotes melanoma invasion by increasing invasive gene activation, such as MMP9." (PMID 33050646, 2020). "The gender-specific expression of a known melanoma tumor suppressor lends credence to the hypothesis that transcriptional regulation by SLNCR and AR contributes to the melanoma gender bias." (PMID 31116991, 2019). "More recent studies have confirmed oncogenic AR activity in melanoma." (PMID 31116991, 2019). "Besides ETS1, we predicted AR, E2F1 and JUND as the most significant regulators in melanoma patients with a TERT promoter mutation." (PMID 31888467, 2019). "AR knockdown significantly decreased proliferation of hormone-deprived melanoma cells (p < 0.0001)." (PMID 31116991, 2019). "Early studies suggested that AR has oncogenic functions in melanoma and that differences in AR function or expression might explain the observed melanoma gender differences." (PMID 31116991, 2019). "Two AR-targeting siRNAs resulted in ~60%–90% of knockdown of AR in 3 melanoma cells." (PMID 31116991, 2019).
melanoma (continued). "To test whether SLNCR and AR cooperatively regulate melanoma proliferation, we introduced short, single-stranded RNA oligonucleotides designed to sterically block the interaction of SLNCR and AR." (PMID 31116991, 2019). "Although AR and SLNCR have been implicated previously in melanoma invasion, this work defines a role of both in the regulation of melanoma proliferation as well, suggesting that AR and SLNCR may be critical regulators of the RGP-to-VGP transition." (PMID 31116991, 2019). "However, it might be argued that while the complex network engaged by steroid receptors (AR, ER alpha or beta, PgR and others) has been deeply investigated in sex-hormone responsive malignancies, it remains still pending in melanoma." (PMID 39837817, 2025). "In contrast, androgen receptor signaling increases the expression and recruitment of DNA-PK and Ku70/Ku80, promoting double-strand break repair, but may also drive tumorigenesis by supporting proliferation and limiting DNA damage sensing in melanoma cells." (PMID 41237160, 2025). "While AR variants have not been linked directly to the risk of malignant melanoma, AR may play a role in melanoma treatment since it has been shown that AR blocking is mediating a better response to BRAF/MEK inhibition." (PMID 40072281, 2025). "AR may represent a critical future target in the evolving landscape of melanoma treatment." (PMID 40564107, 2025). "Thus, the ligand activation of AR might drive melanoma aggressiveness by promoting its invasion and NK immune-escape." (PMID 39837817, 2025). "While our study has identified a previously undisclosed AR-downstream tumorigenic signaling axis, our understanding of the upstream regulation (and deregulation) of AR activity in melanoma—whether it is classically and predominantly androgen-stimulated—remains unclear." (PMID 38326303, 2024). "However, our understanding of AR-regulated cellular and molecular mechanisms in controlling melanoma biology—knowledge that is crucial for informing how AR signaling can be leveraged for patient stratification or therapeutic targeting—has been relatively limited." (PMID 38326303, 2024). "Consequently, AR promotes melanoma metastasis, a process that could potentially be counteracted by restoring MITF expression." (PMID 39597836, 2024). "Thus, increased AR expression in melanoma cells subverts the transcriptional response of melanoma cells to BRAF inhibition, with suppression of pro-apoptotic, immunomodulatory, and antigen presentation pathways and enhancement of pathways implicated in tumor progression and BRAFi resistance." (PMID 37838724, 2023). "To identify genes or sets of genes that are permanently modulated by increased AR expression and may account for their long-term BRAFi resistance, we compared the transcriptional profiles of the three melanoma cell lines plus/minus AR overexpression under basal conditions." (PMID 37838724, 2023). "To further elucidate whether AR expression can influence the immunogenicity of melanoma cells and the immune infiltrates in the tumor microenvironment, we used an immunocompetent model system based on the injection of the mouse melanoma cell line YUMM1.7 into syngeneic mice (BL6 strain)." (PMID 33112375, 2021). "A similar number of AR-Ku70 and AR-dependent Ku70/80-RNA Pol II complexes could be detected in melanoma cell lines with substantially different total AR levels, suggestive of a minor pool of this protein being selectively involved in Ku70/80 anchoring function." (PMID 33112375, 2021). "Moreover, linc00673 and AR might act together to regulate p21 (a primary inhibitor of cyclin-dependent kinases) and subsequently enhance melanoma cell proliferation and tumor growth." (PMID 34231850, 2021). "Since AR-mediated transcription program has been linked to tumorigenesis, the SLNCR1-mediated increase in AR-dependent transcriptional activity in melanoma might explain higher metastatic rate and lower OS of male melanoma patients." (PMID 34638331, 2021).
melanoma (continued). "Furthermore, the activation of the non-genomic pathway, via the combination of the epidermal growth factor receptor (EGFR) and AR, enhanced AR activity itself and modified the melanoma-associated antigen protein-A11 (MAGE-A11), improving melanoma proliferation." (PMID 32645881, 2020). "It is important to note that SLNCR but not AR expression is associated with shorter overall melanoma survival and may be required for mediating gender-specific differences in AR activity." (PMID 31116991, 2019). "Here, we uncover a mechanistic link between AR signaling and autophagic resistance in BRAFV600-mutant melanoma." (PMID 41839860, 2026). "AR inhibitors, such as AZD3514, ARCC4, and enzalutamide, decrease EGFR and SERPINE1 expression and reduce tumorigenicity in BRAF inhibitor-resistant melanoma cells." (PMID 40940929, 2025). "Specific blockade of ADAM10 or androgen receptor impairs the androgen-induced MICA shedding and melanoma immune-escape." (PMID 39837817, 2025). "Of the 4 genes, androgen stimulation resulted in significant downregulation of FUK and upregulation of FUT4—suggesting that AR regulates FUK and FUT4 expression in melanoma cells (left)." (PMID 38326303, 2024). "Here the authors show that androgen-activated AR transcriptionally upregulates fucosyltransferase 4, which fucosylates L1CAM and promotes melanoma invasiveness by disrupting adherens junctions." (PMID 38326303, 2024). "Here, we delineate a previously undisclosed mechanism by which androgen-activated AR transcriptionally upregulates fucosyltransferase 4 (FUT4) expression, which drives melanoma invasiveness by interfering with adherens junctions (AJs)." (PMID 38326303, 2024). "Recent studies in male melanoma and male breast cancer (MBC) have identified significant roles played by the androgen receptor (AR) and AXL in cancer progression and prognosis." (PMID 39597836, 2024). "SLNCR binds with the androgen receptor adjacent to SLNCR’s conserved region, and overexpression leads to increased melanoma invasion." (PMID 38095719, 2024). "Conversely, genes of the EGFR and TGF-ß pathways involved in melanoma progression and targeted drug resistance were induced by DAB treatment in AR overexpressing cells, to a much greater extent than in control cells." (PMID 37838724, 2023). "To assess the functional significance of these findings, we infected three different melanoma lines (A375, WM9, and M14) with an AR overexpressing lentivirus (AR OE) versus LacZ-expressing control (CNTRL)." (PMID 37838724, 2023). "Paralleling these results, ChIP-seq analysis revealed a significant augmentation in AR binding to target genes induced in melanoma cells after 48 h of DAB treatment, including the AR gene itself." (PMID 37838724, 2023). "Broader gene set enrichment analysis (GSEA) of the combined transcriptomic profiles of all examined melanoma cell lines, revealed a selective enrichment of genes related to TGF-ß and EGFR signaling in those overexpressing AR or selected with BRAFi resistance." (PMID 37838724, 2023). "Researchers found that lncRNA-SLNCR interacts with AR and regulates the combination of AR- and EGR1-specific genomic sites, which cooperate with growth-related downstream regulatory genes to promote the proliferation of melanoma." (PMID 36601121, 2022). "Taking advantage of oligonucleotides binding to the AR N-terminal domain or AR RNA motif to block the interaction between SLNCR and AR represents a feasible therapeutic strategy in the process of melanoma." (PMID 36601121, 2022). "Further in vitro and in vivo studies found that AR increased MITF protein degradation by modulating miRNA‐539‐3p/USP13 signalling, which resulted in increased melanoma cell invasion by increasing the expression of the receptor tyrosine kinase AXL." (PMID 35452181, 2022).